EGFR (epidermal growth factor receptor)
Diseases named in the same sentence as EGFR in open-access papers (continued):
Sharing a sentence is not in itself a finding about the gene and the disease.
lung cancer (continued). "Amplification of the EGFR gene is relatively common in lung and other cancers, and may be associated with mutations of the TK domain in lung cancers or of the extracellular domain in glioblastomas." (PMID 17455987, 2007). "In particular, in lung cancer EGFR mutations or EGFR amplification could predict response to EGFR tyrosine kinases inhibitors." (PMID 17876336, 2007). "Lung cancers driven by mutated EGFR are highly responsive to TKI therapy." (PMID 17667926, 2007). "DNA sequence variations in the EGFR gene may lead to alteration in the production and/or activity of the EGFR, thereby causing interindividual differences in lung cancer susceptibility." (PMID 17956637, 2007). "To test this hypothesis, we investigated the association between polymorphisms in the EGFR gene and the risk of lung cancer in a Korean population." (PMID 17956637, 2007). "Future studies on the other EGFR sequence variants and their biological function are also needed in order to understand the role of the 181946C>T polymorphism in determining the risk of lung cancer." (PMID 17956637, 2007). "Therefore, additional studies are needed to detect the other functional variants in the EGFR gene and their associations with lung cancer." (PMID 17956637, 2007). "Abnormalities in EGF-EGFR signaling, such as mutations that render the EGFR hyperactive or cause overexpression of the wild-type receptor, have been found in a broad range of cancers, including carcinomas of the lung, breast, and colon." (PMID 17973573, 2007). "Therefore, exons 18, 19, and 21 in the EGFR gene were sequenced from 23 lung cancer cell lines, in order to assess mutations in the tyrosine kinase domain." (PMID 17150102, 2006). "Although tumour tissue, such as that obtained by surgical resection or transbronchial biopsy, has usually been used for analysis of EGFR mutations in lung cancer, a small number of patients with NSCLC can be diagnosed purely on the basis of cytology using small numbers of cancer cells." (PMID 17047654, 2006). "Another study demonstrated an association between EGFR mutations and increased EGFR gene copy numbers in the human lung cancer cell line H3255, although a large-scale study found that the presence of mutations was not correlated with either the expression or copy number of EGFR." (PMID 17047654, 2006). "The recent results with gefitinib in lung cancer patients with mutations in the EGFR gene are striking but only a minority of the lung cancer population may have this mutation." (PMID 16136026, 2005). "We examined EGFR gene mutations within exons 18–21 and their correlations to clinico-pathological factors and other genetic alterations in tumour specimens from 154 patients who underwent resection for lung cancer at Kyoto University Hospital." (PMID 16052218, 2005). "Unfortunately, EGFR mutations are only found in a minority of patients with lung cancer." (PMID 15696205, 2005). "A receptor for androgens has been reported to occur in NSCLCs and there may be cooperative interaction between the hormones and active mutations of EGFR during the development of lung cancer." (PMID 15870715, 2005). "In the present study, using fresh-frozen tissue from 190 unselected lung cancer patients, quantification of EGFR (EGFR(ELISA)) using a recently developed enzyme-linked immunosorbent assay (ELISA) technique was compared with results (EGFR(IHC)) obtained using immunohistochemistry (IHC)." (PMID 9662257, 1998). "Although third-generation EGFR-TKIs, such as Osimertinib, have provided effective treatment options for patients with the T790M mutation, resistance inevitably occurs after treatment with these agents, limiting the long-term survival of patients with advanced EGFR-mutated lung cancer." (PMID 41257744, 2025).
lung cancer (continued). "Additionally, patients with EGFR-mutated lung cancer, positive for RET fusions at the time of progression on osimertinib, who received the combination of the third-generation TKI and the RET inhibitor selpercatinib, gained clinical benefit associated with a safety profile." (PMID 40243603, 2025). "Similarly, in lung cancer, elevated epidermal growth factor receptor (EGFR) expression has been tentatively linked to CXCR4 induction, correlating with poor clinical outcomes; however, further mechanistic validation is required to establish this relationship conclusively." (PMID 40607416, 2025). "Currently, precision treatment options for lung cancer primarily depend on its histologic subtype and genetic characteristics, for instance, tyrosine kinase inhibitors (TKIs) are preferred for patients with mutations or fusions in genes such as the epidermal growth factor receptor." (PMID 41113459, 2025). "In addition, EGFR 19del mutation [HR = 0.684, 95% CI (0.504–0.928), p = 0.015], a history of lung cancer surgery [HR = 0.558, 95% CI (0.381–0.816), p = 0.003] and no bone metastasis [HR = 0.673, 95% CI (0.498–0.911), p = 0.010] were significantly associated with longer OS." (PMID 39741120, 2025). "Interestingly, EGFR 19del mutation was present in these resistant cells, which indicated that there might be some other reason initiating gefitinib resistance in these lung cancer cells." (PMID 39744423, 2025). "These subregions are hypothesized to reflect underlying biological differences and have been used to predict several cancer‐relevant biomarkers, including EGFR mutation and nodal status in lung cancer, HER2 status in breast cancer, and Ki‐67 expression in laryngeal cancer." (PMID 41422495, 2025). "For example, if the lung cancer cell line PC9 was exposed to an EGFR inhibitor, a subset of the typically susceptible cells developed resistance by adopting a seemingly reversible epigenetic state, which could be mitigated by the administration of a histone deacetylase inhibitor." (PMID 40342734, 2025). "Moreover, PM2.5 levels were linked to higher EGFR-mutant lung cancer in England, South Korea, and Taiwan, with rates rising by 0.63 (P = 0.0028), 0.71 (P = 0.0091), and 1.82 (P = 4.01 × 10−6) per 100,000 individuals for each 1 μg/m3 increase in PM2.5, respectively." (PMID 39578555, 2025). "For some diseases such as lung cancer with canonical driver alterations, detection of individual driver variants (e.g., EGFR, KRAS) can offer a measure of ctDNA shed, yet the same could be feasible in other tumor types such as pancreatic, prostate, bladder, breast, and colorectal cancer." (PMID 40027147, 2024). "In addition, our investigation identified several targeted therapy drugs that displayed efficacy in their target mutated cell lines, including taselisib and alpelisib (PIK3CA inhibitor) in PIK3CA-mutated CRC, and canertinib and dacomitinib (EGFR inhibitors) in EGFR-mutated lung cancer." (PMID 37863651, 2024). "However, studies have found that lung cancer patients with an EGFR mutation are more likely to have an older age at diagnosis, and therefore may not be the reason for our findings." (PMID 38388856, 2024). "Gaining an understanding that the activation mutation in the kinase domain of the epidermal growth factor receptor (EGFR) was in close correlation with the sensitivity/resistance to tyrosine kinase inhibitor-based drugs (TKIs) was achieved via studies conducted using lung cancer cell lines." (PMID 39796653, 2024). "Therefore, in the treatment of EGFR mutation-positive lung cancer brain metastases, radiotherapy-first can achieve better local control by directly acting on brain metastases, which has the advantages of quickly relieving symptoms and improving neurological function." (PMID 38434971, 2024).
lung cancer (continued). "Additionally, we suggest that additional pre-clinical studies be initiated to evaluate the efficacy of dacomitinib as a possible therapeutic for EGFR-mutant lung cancer patients harboring ECD mutations, which are routinely observed as lung cancer somatic mutations." (PMID 38548752, 2024). "• Altered drug targets: Cancer cells may acquire genetic alterations that modify the targets of chemotherapy treatments, rendering them ineffective—for instance, mutations in drug target genes like the epidermal growth factor receptor (EGFR) in lung cancer, leading to resistance to EGFR inhibitors." (PMID 38434679, 2024). "Moreover, in another cohort of 121 patients also presenting metastatic EGFR-mutated lung cancer with BM and treated by osimertinib, an upfront SRT treatment of all BMs revealed a better OS outcome compared to osimertinib alone (HR = 0.37, 95% CI 0.16–0.87, p = 0.021)." (PMID 38730695, 2024). "This study provides valuable insights into the prevalence of EGFR mutation in our setting, which is similar to those reported in the literature for Latin American and European series, as well as clinical characteristics, treatment and outcomes in stage IV lung cancer patients." (PMID 39421175, 2024). "As overexpression of EGFR on the surface of lung cancer cells has been linked with their malignant behavior, we anticipated that a ligand that targets EGFR could be used for lung cancer therapeutics if it were conjugated on the surface of EVs." (PMID 39453005, 2024). "However, there is a lack of relevant research reports on whether it can be used to predict EGFR mutations in lung cancer." (PMID 39735601, 2024). "Variants in EGFR may lead to cancer signalling pathways, such as in lung cancer." (PMID 38245692, 2024). "Moreover, the lncRNA colorectal neoplasia differentially expressed has been implicated in impairing apoptotic activity and promoting resistance to osimertinib and afatinib via the eIF4A/MUC1/EGFR pathway in (osimertinib and afatinib-resistant) EGFR-mutated lung cancer cells." (PMID 39324002, 2024). "Therefore, termination of pregnancy in lung cancer patients requires heightened vigilance, especially in cases associated with EGFR mutations, as the disease may worsen dramatically following cesarean section or abortion." (PMID 37916176, 2023). "Furthermore, it is yet unknown whether MMP11 is related to immune escape in lung cancer, particularly in individuals with EGFR mutation-positive LUAD." (PMID 36756152, 2023). "Interestingly, the risk of BM seems to be 2-3 times higher in EGFR-mutated lung cancers compared to wildtype, and one third of these patients will develop intracranial progression sometime during their disease course, underscoring high neurotropism of these EGFR-mutant tumors." (PMID 36910642, 2023). "Thus, to effectively prevent and treat pleural metastasis, therapeutic strategies which block C5-related signaling could be considered to improve the unique immunological characteristics in the pleural ecosystem in lung cancer patients with EGFR mutation." (PMID 37649596, 2023). "Moreover, by analysing EV-DNA, it was possible to detect three additional T790 mutant cases in patients sensitive to EGFR-TKI and two more cases in patients with acquired resistance, suggesting that liquid biopsy using EV-DNA is promising for the detection of low-rate EGFR mutations in lung cancer." (PMID 37296932, 2023). "In addition to these well-studied common and rare EGFR mutations, EGFR variants of uncertain significance (VUS) were observed in lung cancer patients, but the clinical relevance and TKI sensitivity of these VUSs are largely unknown." (PMID 36829178, 2023). "Furthermore, after adjusting for stage, histology, EGFR mutation, age, smoking, and surgery, multivariate analysis revealed that lung cancer patients with greater blood IGFBP2 had a worse survival result, with a hazard ratio of 8.22 (95% CI 1.78–37.92, p = 0.007)." (PMID 38001653, 2023).
lung cancer (continued). "✓ Aberrant methylation at the promoter region of RASSF1A and GADD45β inversely correlates with protein expression and is linked to the acquisition of TKI resistance in lung cancer cells.✓ Cell treatment with 5-Aza-CdR could partially restore the sensitivity of cells to EGFR-TKI." (PMID 37152062, 2023). "Hence, exploring whether the effect of PHF23 on ACTN4 protein stability is implicated in the resistance process to EGFR-TKIs could provide a new target for combating drug resistance in lung cancer." (PMID 37626047, 2023). "Lung cancer is known to cause the highest number of BM with an incidence of BM in literature ranging from 20% up to as high as 56% of all lung cancer patients depending on histological type, epidermal growth factor receptor (EGFR) mutation status and stage of disease." (PMID 36695975, 2023). "Notably, mutated EGFR in lung cancer and KRAS in colorectal cancer are therapeutic targets of FDA‐approved drugs, and their lower carrier rates in early‐onset cancers may restrict relevant drug applications." (PMID 37610374, 2023). "Besides, β-AR pathway can modulate lung cancer cell resistance, and some works indicate that beta-blockers can slow down the onset of therapeutics resistance especially those associated or interacting with EGFR." (PMID 37696458, 2023). "Furthermore, EGFR mutations involving tyrosine kinase identified in lung cancer may be more susceptible to TKI than GBM." (PMID 38201528, 2023). "Patients with EGFR mutations may be more sensitive to changes in hormonal and inflammatory responses in vivo, indicating the need for individualized formulation of management measures for lung cancer in pregnancy with specific driver mutations." (PMID 37916176, 2023). "However, the relationship between the efficacy of osimertinib and protein expression of VEGF family members in patients with advanced non‐small cell lung cancer (NSCLC) harboring EGFR mutations remains unclear." (PMID 37605832, 2023). "However, smokers or former smokers still made up approximately 30% of the study population that may likely reflect the proportion of smokers or former smokers with EGFR mutated lung cancer in the real world." (PMID 35209919, 2022). "In addition, the EGFR exon 20 insertion mutations may change the resistance of lung cancer to EGFR inhibitors." (PMID 36011604, 2022). "In addition, cfDNA has been used to detect EGFR mutations (exon 19 deletion or exon 21 (L858R) mutations) in selecting NSCLC cancer patients who may benefit from treatment with EGFR-TKIs and in identifying drug resistance mutations in lung cancer patients." (PMID 35372000, 2022). "Moreover, EGFR mutation was discovered to be the first molecular change in lung cancer." (PMID 35663041, 2022). "Additionally, intratumor Haemophilus parainfluenzae is associated with an increased risk of EGFR+ nonsmall cell lung cancer and may possibly drive lung cancer oncogenesis through NTHi-driven inflammation." (PMID 36362038, 2022). "Recent studies have found co-occurring genomic alterations were common in EGFR-mutated lung cancers, especially in advanced-stage cancers; however, the biological significance of these co-occurring events and their correlation with clinical features were largely unknown." (PMID 35643428, 2022). "Besides, 19 patients harboring EGFR mutations, the most common driver mutation of lung cancer, were involved which could shed light on neoadjuvant treatment for EGFR-mutant NSCLC in a way." (PMID 36123526, 2022). "A low TMB may also explain the limited efficacy of ICIs in EGFR-/ALK-mutated lung cancer." (PMID 35407463, 2022).
lung cancer (continued). "Our findings revealed that both natural and synthetic compounds having strong associations with EGFR protein could be potential candidates to inhibit the interaction between HMs and lung cancer protein and can also be used as an alternative for the prevention and treatment of lung cancer." (PMID 35607306, 2022). "However, the majority of previous studies have focused on EGFR mutations in primary lung cancer." (PMID 35964032, 2022). "Our data were found in patients with unknown resistance to treatment, and although the number of patients was low and data were precursory, in the evolution of EGFR-mutated lung cancer, NF1 could be playing an unknown role in disease progress and resistance to targeted therapies." (PMID 35884384, 2022). "For example, research suggests that the EGFR mutation may be more prevalent in people of East Asian ancestry, which may be associated with the disproportionately high representation of Asian individuals in some lung cancer studies." (PMID 33877309, 2021). "Although lung cancer patients harbouring activating mutations in EGFR display initial response to TKIs targeting the activating mutation, most patients acquire resistance after a progression-free period of about 10 months due to secondary mutations in the kinase domain of EGFR." (PMID 34610265, 2021). "Therefore, ANXA1 may be an attractive target for lung cancer therapy and to enhance the treatment effects of Osimertinib on lung cancer cells with EGFR mutations." (PMID 34439260, 2021). "To develop a mouse model that could recapitulate osimertinib resistance caused by MET amplification in patients with EGFR-mutated lung cancer, we took advantage of a mouse strain in which liver carcinoma develops upon induction of human WT MET expression in the liver." (PMID 34298655, 2021). "Since we found that irradiation specifically suppressed STAT1 and STAT3 phosphorylation in IFNγ-treated A549 cells in this study, we speculated that STAT3 caused radioresistance was mediated by overexpression and activation of mutated EGFR in lung cancer after survived in RT treatment." (PMID 34685495, 2021). "Moreover, only a small fraction of patients with lung cancer with EGFR mutations (<5%) experience a complete response, although the EGFR mutation is a truncal mutation and is homogeneously distributed (i.e., virtually all tumor cells harbor the same EGFR mutation)." (PMID 34202566, 2021). "According to prior studies, EGFR rs2302535 had an association with radiation-induced esophagitis in lung cancer patients, and rs11238349 might be involved in the pathway in the development of prostate cancer, but the relationship between these two SNPs and the kidney has not been indicated." (PMID 34501555, 2021). "EGFR TKIs may also decrease the risk of BMs in lung cancers harboring EGFR mutations." (PMID 34071176, 2021). "Therefore, if conversion from tarloxotinib to tarloxotinib‐E in tumor tissues of human subjects is confirmed, tarloxotinib might be used to treat lung cancers with EGFR exon 20 mutations." (PMID 33710795, 2021). "According to these findings, miR-27a could down-regulate MET and EGFR by targeting their 3′ UTRs directly or indirectly through Sprouty2; consequently, the underlying mechanism of the MET and EGFR axis regulation may emerge as new strategies in lung cancer treatment." (PMID 34830377, 2021). "Furthermore, it has been shown that effective targeted therapies against EGFR depend on the KRAS and BRAF status in patients with metastatic CRC and lung cancer, indicating that mutations could influence the activation of the EGFR pathway." (PMID 34147083, 2021). "However, it is unknown how the inhibition of EGFR activity induces these epigenetic changes only in a small fraction of EGFR-mutated lung cancer cells." (PMID 34202566, 2021).